CNBD2 (cyclic nucleotide binding domain containing 2)
Description:
Essential for male fertility. Plays an important role in spermatogenesis and regulates sperm motility by controlling the development of the flagellar bending of sperm.
Synonyms: C20orf152; dJ954P9.1; CNMPD1
Tractability: No criterion of Open Targets' tractability assessment is met for any kind of drug.
Gene: Protein-coding gene on chromosome 20 (35,954,564 to 36,030,700, forward strand). Ensembl gene ENSG00000149646.
Subcellular location: Cytoplasm, cytosol
Subcellular location (Human Protein Atlas): Mid piece; Nucleoli; Actin filaments; Cytosol
Gene Ontology:
Molecular function: cAMP binding
Biological process: spermatogenesis
Cellular component: sperm midpiece; cytosol
Genetic constraint (gnomAD): Loss-of-function variants: 54 observed, 57.74 expected, observed/expected ratio (o/e) 0.94, 90% interval 0.75 to 1.17. The upper end of that interval is the gene's LOEUF score, 1.17, which puts it in group 5 of 6, group 1 being the genes least tolerant of losing a copy. Missense variants: 650 observed, 705.2 expected, observed/expected ratio (o/e) 0.92, 90% interval 0.86 to 0.98. Synonymous variants: 220 observed, 254.9 expected, observed/expected ratio (o/e) 0.86, 90% interval 0.77 to 0.96.
Homologues: Orthologues: chimpanzee CNBD2 (87% identical), macaque CNBD2 (87% identical), dog CNBD2 (73% identical), rabbit CNBD2 (71% identical), pig CNBD2 (69% identical), guinea pig CNBD2 (68% identical), mouse Cnbd2 (65% identical), rat Cnbd2 (62% identical), tropical clawed frog cnbd2 (31% identical), Drosophila melanogaster CG12698 (14% identical), Drosophila melanogaster CG14693 (14% identical), Drosophila melanogaster CG8958 (14% identical).
Diseases named in the same sentence as CNBD2 in open-access papers:
CNBD2 is named in the same sentence as 2 diseases in open-access papers, as found by Europe PMC text mining. Sharing a sentence is not in itself a finding about the gene and the disease.
CNBD2 shares sentences with these, for which no sentence is quoted: male infertility (1 paper); Obesity (1).